TOP1 (DNA topoisomerase I)
Diseases named in the same sentence as TOP1 in open-access papers (continued):
Sharing a sentence is not in itself a finding about the gene and the disease.
Alzheimer disease (1 paper, 2023). A progressive, neurodegenerative disease characterized by loss of function and death of nerve cells in several areas of the brain leading to loss of cognitive function such as memory and language. "In particular, L1-70 and its interaction with TOP1 in nuclei has been proposed to play an important role in the pathogenesis of Alzheimer’s disease." (PMID 36768419, 2023).
Angelman syndrome (1 paper, 2016). A neurogenetic disorder characterized by severe intellectual deficit and distinct facial dysmorphic features. "In summary, TOP1 poisons could be useful for the treatment of Angelman syndrome or other genetic disorders that may be suppressed by blocking expression of long genes." (PMID 27181710, 2016).
autism (1 paper, 2023). Persistent deficits in social interaction and communication and interaction as well as a markedly restricted repertoire of activity and interest as well as repetitive patterns of behavior. "Moreover, mutations in TOP1 are reported to be associated with autism." (PMID 36768419, 2023). "Because TOP1 and L1 are associated with autism and because TOP1 inhibitors and knockdown of TOP1 reduced the expression of extremely long genes that are associated with autism, we investigated whether the interaction of L1 with TOP1 affects gene expression of autism-associated genes." (PMID 36768419, 2023). "Since L1-70’s interactions with TOP1, PPARγ and NDUFV2 contribute to the expression of two essential long autism genes and regulate important neuronal functions, we propose that L1 may not only ameliorate neurological problems, but also psychiatric dysfunctions." (PMID 36768419, 2023).
Autoimmunity (1 paper, 2018). The occurrence of an immune reaction against the organism's own cells or tissues. "It has, however, been shown that autoimmunity in SSc may be dependent on the formation of ROS-induced oxidized neoepitopes that may induce the breach of tolerance against DNA topoisomerase I and autoimmunity." (PMID 30177933, 2018).
Batten’s Disease (1 paper, 2025). "Other proteins enriched in UBQLN24XALS IPs included BTBD2, which encodes a Ub E3 ligase involved in cytoskeletal dynamics and Top1-mediated chromatin relaxation, and phospholipase B D2 (PLBD2), a lysosomal phospholipase that has been implicated in the lysosomal storage disorder, Batten’s Disease." (PMID 41561437, 2025).
colon adenocarcinoma (1 paper, 2022). "TOP1 mutations can lead to camptothecin resistance in the human HCT116 colon adenocarcinoma cell line when exposed to SN38, a water-soluble camptothecin derivative." (PMID 35149760, 2022).
cyst (1 paper, 2023). A sac-like closed membranous structure that may be empty or contain fluid or amorphous material. "Unexpectedly, germline-specific top1 knockdown with CPT treatment also led to significant two-cell cyst loss compared with top1RNAi germarium without CPT treatment, which might be attributed to germ cell loss in some cases from top1RNAi germarium with CPT treatment." (PMID 36675143, 2023).
E. coli infection (1 paper, 2022). "Here, the expression of nuclear genes POLG, SSBP1, TWNK, and TOP1 during E. coli infection was consistent with that of mtDNA." (PMID 36430657, 2022).
ear infection (1 paper, 2022). A viral or bacterial infection that affects the external, middle, or inner ear. "In wheat ear infection assays, top1 mutants of F. graminearum and F. culmorum demonstrated exceptionally reduced virulence." (PMID 35448601, 2022).
endometrium carcinoma (1 paper, 2022). "The median numbers of mutations in these five types of tumors, ranging from 125 in endometrium carcinoma to 302 in skin malignant melanoma, were significantly higher than that in All_tumors but still ~8 to 3-fold lower than in the tumors with Top1 mutations." (PMID 35291312, 2022).
Friedreich ataxia (1 paper, 2019). An inherited condition that affects the nervous system and causes movement problems. "Chemical inhibition of TOP1 in Friedreich Ataxia (FRDA) model cell lines with FXN expansions potentiates R-loop accumulation and H3K9me2 enrichment, providing further evidence that R-loop formation increases deposition of this repressive mark." (PMID 31225499, 2019).
germ cell tumours (1 paper, 2002). "DNA topoisomerase I is the target for several new drugs and a potential candidate treatment for chemorefractory germ cell tumours." (PMID 12237772, 2002).
hepatitis C (1 paper, 2019). "To note, all symptom checkers, whether for combined HIV and hepatitis C, HIV alone or hepatitis C alone had poor diagnostic accuracy in regards to Top1 (<20%), Top3 (<35%), Top10 (<40%), Listed at All (<45%)." (PMID 30869052, 2019).
hereditary ataxia (1 paper, 2014). An instance of an atactic disorder that is caused by an inherited genomic modification in an individual. "Base damage and topoisomerase I (Top1)-linked DNA breaks are abundant forms of endogenous DNA breakage, contributing to hereditary ataxia and underlying the cytotoxicity of a wide range of anti-cancer agents." (PMID 24335147, 2014).
Huntington disease (1 paper, 2022). Huntington disease (HD) is a rare neurodegenerative disorder of the central nervous system characterized by unwanted choreatic movements, behavioral and psychiatric disturbances and dementia. "Whether TOP1 DNA breaks are sources of genomic instability in Huntington’s disease (HD) is unknown." (PMID 35224690, 2022).
Hyperkalemia (1 paper, 2021). An abnormally increased potassium concentration in the blood. "It is clear from the plot that antipropulsives, coxibs, drugs for treatment of hyperkalemia and hyperphosphatemia, oral bowel cleansers, other antineoplastic agents, and TOP1 inhibitors were associated with death in more than 10% of the cases in each category." (PMID 34381361, 2021). "On the other hand, a risk of death outcome greater than 10% was found for antipropulsives, coxibs, drugs for treatment of hyperkalemia and hyperphosphatemia, oral bowel cleanser, other antineoplastic agents, and TOP1 inhibitors." (PMID 34381361, 2021).
medulloblastoma (1 paper, 2018). A malignant, invasive embryonal neoplasm arising from the cerebellum. "High expression of MRP1 (89%, 8/9 tumors), TUBB3 (86%, 18/21 tumors), PTEN (85%, 28/33 tumors), TOP2A (84%, 26/31 tumors), thymidylate synthase (TS; 80%, 24/30 tumors), RRM1 (71%, 15/21 tumors), and TOP1 (63%, 19/30 tumors) were found in medulloblastoma." (PMID 29869738, 2018). "We also found TOP1 expression, which may have been an unappreciated confounder of response to irinotecan in children with recurrent medulloblastoma." (PMID 29869738, 2018).
osteosarcoma (1 paper, 2013). A usually aggressive malignant bone-forming mesenchymal neoplasm, predominantly affecting adolescents and young adults. "The significant correlation between TOP1 and TOP2A gene copy variations reinforced the molecular basis of TOP1 and TOP2A linked expression in malignant osteoblasts and, consequently, in pediatric osteosarcomas." (PMID 24216996, 2013).
ovarian serous cancer (1 paper, 2015). "Thirty five cases out of 316 ovarian serous cancer contained TOP1 alterations including 1 amplification, 1 mutation, and 33 mRNA dysregulations." (PMID 25884494, 2015).
paraganglioma (1 paper, 2014). A benign or malignant neoplasm arising from paraganglia located along the sympathetic or parasympathetic nerves. "Our findings provide proof of principle for use of TOP1 inhibitors against pheochromocytoma/paraganglioma and suggest novel strategies for enhancing efficacy and reducing toxicity by optimizing the combination and timing of their use in conjunction with other drugs." (PMID 24516563, 2014).
peritoneal cancer (1 paper, 2022). A peritoneum cancer that is located in the inside of the abdomen. "In addition, CRLX101 containing camptothecin, a DNA topoisomerase-I inhibitor, encapsulated in cyclodextrin-PEG copolymers NPs has already achieved phase I/II clinical trials in patients with rectal, ovarian, tubal, and peritoneal cancer." (PMID 36135572, 2022).
pheochromocytoma (1 paper, 2014). "We then used a mouse pheochromocytoma cell line (MPC) as a model to further test camptothecin and other TOP1 inhibitors in conjunction other drugs." (PMID 24516563, 2014).
renal cell carcinoma (1 paper, 2012). "In practice, these Top1 inhibitors exert a promising anticancer effect in the treatment of renal cell carcinoma." (PMID 22754346, 2012). "A series of indenoisoquinolines displaying potent Top1 inhibitory activity in human renal cell carcinoma cell line SN12C were selected to establish 3D-QSAR models using CoMFA and CoMSIA methods." (PMID 22754346, 2012).
spinocerebellar ataxia with axonal neuropathy (1 paper, 2018). "In non-replicating cells, TOP1 cleavage complexes are primarily repaired by TDP1, and TDP1 mutations cause the neurodegenerative disease spinocerebellar ataxia with axonal neuropathy (SCAN-1)." (PMID 29584802, 2018).
T-cell leukemia (1 paper, 2019). A malignant disease of the T-lymphocytes in the bone marrow, thymus, and/or blood. "Finally, TCR signaling pathway is a T-cell-specific pathway, and Factor 108 is also enriched with T-cell-driven tumor types (for example, T-cell leukemia), which are the most sensitive to the TOP1-poisons." (PMID 31695042, 2019).
testicular tumours (1 paper, 2002). "The expression of DNA topoisomerase I and IIα were therefore assessed immunohistochemically in a range of testicular tumours, especially those with persistent malignant elements on retroperitoneal lymph node dissection." (PMID 12237772, 2002).
thymoma (1 paper, 2022). A neoplasm arising from the epithelial cells of the thymus. "TOP1 and PRP4 showed moderate elevation across cancer types, and the most pronounced changes for PRP4 were observed in thymoma and kidney chromophobe subtype while the most pronounced changed for TOP1 were observed in lung, stomach and esophagus, and uterine corpus endometrial carcinomas." (PMID 35463320, 2022).
Tinnitus (1 paper, 2024). Tinnitus is an auditory perception that can be described as the experience of sound, in the ear or in the head, in the absence of external acoustic stimulation. "To characterize the role of the tinnitus-related top1 HDP, BDNF, in the AP, AcouStim, and Tin processes, and to identify pathways of BDNF, we searched for proteins that showed interactions with HSIPs of BDNF and thus extended the number of proteins." (PMID 39062188, 2024).
tuberculosis (1 paper, 2009). A chronic, recurrent infection caused by the bacterium Mycobacterium tuberculosis. "Mycobacterium tuberculosis DNA topoisomerase I is an attractive target for discovery of novel TB drugs that act by enhancing the accumulation of the topoisomerase-DNA cleavage product." (PMID 19519900, 2009).
cancer (248 papers, 2006 to 2026). A tumor composed of atypical neoplastic, often pleomorphic cells that invade other tissues. "Exploiting the cytotoxic effects of TOP1cc-associated genome instability, TOP1 inhibition is standard of care for several difficult to treat cancers, including metastatic breast cancer and relapsed ovarian cancer." (PMID 40796804, 2025). "We previously showed that mutations in Top1 correlate with high mutation frequencies, particularly at the potentially G4-forming sequences in the cancer genomes." (PMID 41009588, 2025). "We propose macroH2A1 alternative splicing as an epigenetic modulator of TOP1-associated genome maintenance and a potential cancer vulnerability." (PMID 40796804, 2025). "This suggests that there are likely various mechanisms underlying the roles of TOP1 in contributing to alterations in DoG production in human cancers." (PMID 38959318, 2024). "Our results underlie the significance of DoG RNAs and TOP1-dependent regulation of DoG RNAs in diversifying and modulating the cancer transcriptome." (PMID 38959318, 2024). "The idea was simple: stopping PARP would prevent repair of DNA breaks caused by TOP1 inhibitors, leading to more cancer cell deaths." (PMID 39456202, 2024). "The impact of TOP1 on aberrant transcriptional control in CRC and the mechanisms underlying effective TOP1 targeting for cancer treatment largely remain to be elucidated." (PMID 38959318, 2024). "The mutational signal of Top1-induced events, namely 2–5 bp deletions at tandem repeats, has been applied to demonstrate that these events also occur in human cancers." (PMID 39408578, 2024). "Although the importance of Top1-induced mutations in cancer requires further exploration, it is clear that Top1 is the driver of specific mutational processes, with the mutations induced by Top1 action seen in cancer cells." (PMID 39408578, 2024). "Irinotecan (CPT-11) is a chemotherapeutic agent that causes cancer cell killing by poisoning topoisomerase I (Top1) in the cell." (PMID 37108395, 2023). "Initial exposures to SN-38 generate reversion of a number of “cancer” alleles to the reference genome alleles, which are more resistant to Top1-induced DSBs, which in turn creates a protective mechanism against subsequent exposures." (PMID 37240063, 2023). "The disproportionately high loss of the “cancer allele” indicated that Top1-generated DSB took place in this allele preferentially, and it was repaired by copying of the reference genome sequence from the homologous chromosome." (PMID 37108395, 2023). "Recently, it has been demonstrated that some human cancers harbour RNase H2 mutations, resulting in rNMP accumulation and Top1-mediated genome instability." (PMID 36869098, 2023). "We furthermore show that in cancer genomes, functionally detrimental mutations in Top1 correlate with enrichment of mutations at G4 motifs." (PMID 35291312, 2022). "We show experimentally that ID4 deletions are increased in RNase-H2-deficient cell lines and cancers and delineate a human TOP1-mediated TAM signature (ID-TOP1) that is relevant to both somatic and germline mutagenesis." (PMID 35140396, 2022). "In fact, mutations that reduce Top1 DNA binding and/or cleavage are documented in cancer patients and cells treated with CPT or CPT-derivatives." (PMID 35291312, 2022). "Top1 inhibitors have been widely used in cancer therapies, most of them cause cytotoxicity by trapping the cross-linked DNA-Top1 intermediate, thus interfering with processes such as DNA replication and transcription." (PMID 34544118, 2021). "As is the case for Top2α, compounds that reversibly stabilize Top1cc are termed Top1 poisons since these result in persistent DNA double-strand breaks that cause cancer cells to undergo apoptosis." (PMID 34532656, 2021). "The inactivation of RB1 is frequently assessed in triple-negative BC and is linked to sensitivity to many cancer drugs, including TOP1 inhibitors." (PMID 33670375, 2021).
cancer (continued). "Cancer cells can also become impervious to CPT-treatment through mutations of Top1 that reduce the ability either to bind to duplex DNA or to cleave duplex DNA following binding." (PMID 32059547, 2020). "Silencing of RRM2, the gene encoding for mammalian RNR complex subunit R2, hyper-sensitizes cancer cells to camptothecin, an inhibitor of TOP1, by hampering repair of DNA damage caused by collisions of RFs with TOP1 cleavage complexes." (PMID 32187369, 2020). "A large number of Top1 mutations identified in CPT-resistant cancer cells and patient samples remain uncharacterized." (PMID 32059547, 2020). "In this article, we discuss the characteristics of topoisomerase (DNA) I (TOP1) and its inhibitors, as well as the underlying DNA repair pathways and the use of TOP1 inhibitors in cancer therapy." (PMID 26287259, 2015). "The TOP1 gene copy number, mRNA level, protein level, and enzyme activity are reported to be associated with a poor prognosis in cancer therapy." (PMID 26207989, 2015). "Top1 knockdown that was conducted with small interfering RNA to the level of ~10–20% in cancer cell lines caused genomic instability and replication defects." (PMID 23836376, 2013). "Although Top1 mutations at codon 722 have been identified in several camptothecin-resistant human cancer cell lines, the other mutations have yet to be found." (PMID 23836376, 2013). "We have reported on the development and validation of an enzyme-linked immunosorbent assay (ELISA) for quantifying Top1 levels in cancer cell lines." (PMID 23284638, 2012). "Such pathological function of mutant Top1 could be the underlying cause of secondary cancer development documented in patients following treatment with CPT derivatives." (PMID 41009588, 2025). "Our data show that the impact of Top1Y740* elevates recombination as well as mutations specifically at G4-DNA-forming regions of the genome, closely reflecting the frequent mutations at G4-forming sequences in cancer cells with mutations at C-terminal residues of human Top1." (PMID 41009588, 2025). "Chronic lymphocytic leukemias are often associated with loss of RnaseH2, the key enzyme required for normal ribonucleotide excision repair, thus some cancers may have a mutator phenotype due to the action of Top1 removal of ribonucleotides." (PMID 39408578, 2024). "Top1 poisons cause a transient increase in R loops in cancer cells." (PMID 38787953, 2024). "Since Top1 mis-functioning can lead to genome instability, a plausible hypothesis is that Top1-induced mutations might be found in cancer cells thereby accelerating tumorigenesis." (PMID 39408578, 2024). "Top1-mediated single-strand breaks may facilitate double-strand DNA breaks that, if unrepaired, cause cancer cell death." (PMID 37240063, 2023). "It is therefore reasonable to speculate that the proteolysis of replication-associated TOP1-DPCs is primarily driven by the UPP in certain cancers such as CRC due to their low SPRTN expression." (PMID 37353483, 2023). "Importantly, since compounds inducing TOP1-mediated DPCs are currently used in cancer treatment, understanding the underlying mechanism of the repair pathway is essential for improving the efficiency of combination therapy with TDP1 and MUS81 inhibitors." (PMID 37194054, 2023). "ID4, a signature enriched for deletions (>1 bp) at repeats and microhomology, recently associated experimentally with TOP1 mutational activity in cancer and healthy cells, on the other hand was significantly more prevalent in non-high-risk patients (p < 1.68 × 10−3)." (PMID 37868040, 2023). "In addition to point mutations in Top1, copy number variations of the Top1 gene that associate with resistance were also reported in different cultured cancer cells." (PMID 37108395, 2023). "Therefore, surprisingly, alleles that acquired mutations in the course of cancer development were significantly more prone to Top1-induced double-strand breaks than normal human genome alleles." (PMID 37240063, 2023).